EPS8 (EGFR pathway substrate 8, signaling adaptor)
Diseases named in the same sentence as EPS8 in open-access papers (continued):
Sharing a sentence is not in itself a finding about the gene and the disease.
cancer (continued). "The cancer cell lines A549, Colo320, HepG2, HT-29 and SW620 were Eps8+ and HLA-A24+." (PMID 29515106, 2018). "However, Eps8 and FAK bind to one another directly and are likely part of larger multi-protein scaffolding complexes in cancer cells." (PMID 25359883, 2014). "The results i.e., higher level of Eps8 expression in tumors as compared to their adjacent normal was independent of the grade of the cancers studied." (PMID 20565814, 2010). "The lack of these cancer stem cell markers, specifically SEMA5A (semaphorin 5A), KITL (KIT ligand, stem cell factor), CAV2 (caveolin 2), EPS8 (epidermal growth factor receptor pathway substrate 8) and PKP4 (plakophilin 4), was associated with acquired resistance to radiation in this study." (PMID 33767581, 2021). "Thus, they function as cancer-promoting genes, such as FOXQ1, PHLDA2, LPCAT2, AP1S3, and EPS8." (PMID 32977589, 2020). "Besides a hypoxic profile, DTC tumors also have marked expression of cancer relevant genes such as the metastasis-promoting tetraspanin 8 (TSPAN8), proliferation and migration promoting epidermal growth factor substrate 8 (EPS8)." (PMID 27105499, 2016). "Thus, EPS8 is a TAA and may be utilized as a target in immunotherapy of cancer as well as in hematological malignancies." (PMID 25936538, 2015). "Thus, Eps8 is required for leader bleb formation to drive migration of confined, non-adherent cells in several cancer cell types, independent of the defect driving transformation." (PMID 26163656, 2015). "Thus, Erk activity promotes actin bundling by Eps8 to enhance cortex tension and drive the bleb-based migration of cancer cells under non-adhesive confinement." (PMID 26163656, 2015). "Furthermore, Eps8 depletion did not cause further impairment over that caused by loss of FAK alone, suggesting that Eps8 and FAK are promoting their cancer-associated processes by the same molecular pathway." (PMID 25359883, 2014). "However, when FAK is absent, Eps8 is instead co-recruited with active Src to intracellular puncta that contain autophagy proteins, which we have previously shown SCC cancer cells use to deal with highly active Src that is not tethered to FAK." (PMID 25359883, 2014).
tumor (28 papers, 2009 to 2025). "Due to the importance of EPS8 in response to cisplatin in tumor cells and our identification of a SNP within EPS8 (rs4343077) associated with both cisplatin cytotoxicity and apoptosis, we further evaluated the relevance of EPS8 in sensitivity to cisplatin." (PMID 24367505, 2013). "The restoration of ITSN-1s protein levels promotes the interaction between CBL E3 ubiquitin ligase and Eps8, leading to the increased ubiquitination of Eps8 tumor protein." (PMID 39130630, 2024). "EPS8 mutant-expressing and control cells were injected into the tongues of athymic mice, and tumour formation was monitored." (PMID 32641864, 2020). "Our recent study of PDAC showed that the expression of EPS8 was directly regulated to tumor-suppressive miR-130b-5p." (PMID 32899691, 2020). "This desmoplastic reaction was enhanced following down‐regulation of Eps8 and revealed a clear interaction between αSMA‐positive fibroblasts and invading tumour islands." (PMID 28608476, 2017). "PDAC has been reported to overexpress both αvβ6 and Eps8 7, 23, and consistent with these studies, we found that around 70% of tumours expressed αvβ6 and Eps8 at moderate/high levels." (PMID 28608476, 2017). "Its expression in normal tissue types is relatively low, and it has a pivotal role in tumorigenesis, tumor proliferation, invasion and metastasis; furthermore, the expression levels of EPS8 correlated with disease severity and overall survival of patients." (PMID 25936538, 2015). "Epidermal growth factor receptor pathway substrate 8 (EPS8), whose function is pivotal for tumor proliferation, progression and metastasis, has been found to be overexpressed in most human tumor types, while its expression in normal tissue is low." (PMID 25936538, 2015). "Meanwhile, Rac activation by the IRSp53/Eps8 complex plays an important role in the metastatic behavior of the malignant tumor cell." (PMID 23469231, 2013). "Literature evidence suggested EPS8 knockdown in tumor cell lines increased cellular sensitivity to cisplatin." (PMID 24367505, 2013). "In keeping with this latter possibility, Eps8 hasbeen reported to be unregulated in a variety of tumor types and to bespecifically required for optimal cell migration and invasion in a subset ofmetastatic oral squamous carcinoma cells." (PMID 20532239, 2010). "The analysis revealed that in the training set, the expression of BANF1, CDK2AP2, DDT, LRIG1, MRPL4, and S100A13 was significantly upregulated in tumor samples, and the expression of EPS8, NUCB2, PAF1, PMP22, RABGAP1L, and USO1 was higher in control samples (p < 0.05)." (PMID 41000388, 2025). "EPS8 overexpression levels were also downregulated in tumor samples from nude mice." (PMID 29357910, 2018). "Moreover, epidermal growth factor receptor pathway substrate 8 (EPS8) is overexpressed in most human tumor tissue, while expressed to a lesser degree in normal tissue." (PMID 28509875, 2017). "In late‐stage disease, both αvβ6‐dependent functions are likely to be tumour‐promoting; however, we can speculate that in premalignant disease, the bias towards an Eps8‐expressing, invasive phenotype may help to promote malignant transformation." (PMID 28608476, 2017). "EPS8 upregulation is thus expected to be involved in human carcinogenesis, implying that this gene may be used as a target in tumor immunotherapy." (PMID 25936538, 2015). "EPS8 is an oncoprotein contributing to malignant transformation in tumor cells." (PMID 24367505, 2013). "In tumor tissues, four protective genes (JAK2, IL2RG, EEF1E1, and UBB) showed relatively low expression in the high‐risk group; in contrast, the expression of four risk genes (EPS8, FOXO1, STAT5A, and PAPPA) was more highly in the high‐risk group than that in the low‐risk group." (PMID 34825509, 2021). "Notably, Eps8 plays an important role in driving tumor progression, making it an attractive target." (PMID 29515106, 2018).
tumor (continued). "Finally, the role of Eps8 as a bifunctional actin remodeller further suggeststhat this protein by controlling various actin-based protrusions regulatesoptimal cell locomotion both in physiological and in pathological contexts, suchas during tumor development." (PMID 20532239, 2010). "EPS8 is a scaffolding protein that regulates proliferation and receptor trafficking in solid tumors like PAAD, and its high expression mediates tumor cell migration and disease progression." (PMID 40141028, 2025). "Many other tumor promoters (such as the epidermal growth factor receptor pathway substrate 8 (Eps8), hexokinase 2 (HK2), galactose lectin-3, etc.)are degraded via the CMA pathway to deactivate them and inhibit tumor growth." (PMID 37509689, 2023). "The Eps8 gene was originally identified as a substrate for the EGFR kinase, which is known to promote tumor progression through an EGFR-dependent pathway." (PMID 29515106, 2018). "Taken together, we report the screening and identification of HLA-A*2402-restricted epitopes and evaluated the potential of peptide 327 as an inhibitor of the Eps8/EGFR complex in vitro and in tumor-bearing mice." (PMID 29515106, 2018). "In most cases (37/43 genes), methylation was more frequent in cell lines than primary tumours, however for 6 genes this pattern was reversed (ZNF215: 21% and 42% respectively, DAPK1: 4% and 39%, EPHA3 13% and 32%, SMARCB1: 8% and 27%, EPS8 4% and 21% and MCM2: 0% and 21%)." (PMID 19493342, 2009). "Epidermal growth factor receptor pathway substrate 8 (EPS8) controls various cellular protrusions by regulating actin cytoskeleton dynamics and architecture as well as participates in growth factor activation, therefore promotes cell proliferation and cell survival within tumour." (PMID 36774501, 2023). "The data indicate that blocking Y602-EPS8 leads to a significant reduction in cell proliferation compared to the control, and the effect was comparable to that seen with the FFFF-EPS8 mutant, suggesting that phosphorylation of Y602 in EPS8 is crucial for proliferation of tumour cells in culture." (PMID 32641864, 2020). "Interestingly, the expression of Eps8 correlated with the tumor stage and p16 status but not with anatomical localization of tumors." (PMID 30718984, 2019). "Although the protein expressions of PLAU, GDF11, EPS8 and GH1 in tumor and normal groups were not significantly different, the survival analysis results were consistent with our risk model results." (PMID 36741321, 2023). "Of the 29 candidate compounds tested, EE02 showed remarkable inhibition of the growth of tumor cells with high expression of EGFR and Eps8 and promoted apoptosis, while did not significantly inhibit and promote apoptosis in normal cell lines." (PMID 31118055, 2019). "Since none of members in SOS1/EPS8/ABI1 tri-complex is dispensable in the Rac activation, and ABI1 acts as a scaffold protein, we hypothesize that ABI1 may be an ideal target to design anti-tumor drugs." (PMID 31488087, 2019).
hematological malignancies (3 papers, 2015 to 2026). "Elevated EPS8 expression levels have been found in various solid tumors and several hematological malignancies." (PMID 29357910, 2018). "However, the role of EPS8 in hematological malignancies has not been clarified in detail." (PMID 29357910, 2018).
infection (2 papers, 2009 to 2024). The state of being infected such as from the introduction of a foreign agent such as serum, vaccine, antigenic substance or organism. "The infection of eps8 null neurons with the GFP-tagged Eps8 lentiviral vector led to a significant reduction in the number of axonal filopodia to WT levels." (PMID 19564905, 2009).
EPS8 also shares sentences with these, for which no sentence is quoted: esophageal squamous cell carcinoma (2 papers); adenocarcinoma (1); Alzheimer disease (1); anencephaly (1); cervical squamous cell carcinoma (1); colon cancer (1); colorectal cancer (1); cyclopia (1); esophageal adenocarcinoma (1); hereditary spastic paraplegia (1); Insulin resistance (1); invasive breast carcinoma (1); invasive carcinoma (1); Macrocephaly (1); microcephaly (1); neurological disorders (1); osteosarcoma (1); pituitary adenomas (1); pituitary gland cancer (1); renal dysplasia (1); sensorineural hearing loss (1); spina bifida (1); Stickler syndrome (1); thrombosis (1); thyroid cancer (1); Usher syndrome (1).